GSTM1 (glutathione S-transferase mu 1)
Diseases named in the same sentence as GSTM1 in open-access papers (continued):
Sharing a sentence is not in itself a finding about the gene and the disease.
cancer (continued). "At the same time, a relationship between deletion in the GSTT1 and GSTM1 genes and an increased risk of occurrence for many types of cancer (e.g., liver cancer, breast cancer, cervical cancer, head and neck cancer, esophageal cancer, oral cancer, lung cancer) has been shown." (PMID 39125992, 2024). "GSTM1 gene polymorphism is available to impact carcinogens’ metabolism, and then influence cancer cells’ growth, clarifying that it might be associated with patients’ prognosis." (PMID 37814615, 2023). "Deletion mutation of the GSTT1 and GSTM1 genes may be a risk factor for developing various types of cancer and other chronic diseases associated with delayed exposure to genotoxicants." (PMID 38133349, 2023). "Although most meta-analyses indicate that the GSTT1 null genotype and the GSTM1/GSTT1 null genotype may predispose to an increased risk of cancer development in East Asian population, this hypothesis should be taken into the account with some caution." (PMID 37819495, 2023). "The reduced expression of GSTM1 has been associated with certain cancer types." (PMID 35008958, 2022). "Glutathione S-transferase Mu (GSTM) gene family is group of 5 proteins, GSTM1-5, that play a key role in the detoxification of electrophilic compounds, such as cancer-causing toxins, anticarcinogens and products of oxidative stress via conjugating with glutathione." (PMID 35965498, 2022). "In addition, predictive function of low GSTM2 and GSTM1 were involved in the cell cycle, which is associated with the occurrence of cancers and outcome." (PMID 32539715, 2020). "Therefore, the association of GSTP1/ GSTM1 variants with highly malignant disease and poor prognosis in cancer patients was suggested." (PMID 31646988, 2019). "First, it is well‐established that the GSTM1‐present genotype is associated with elevating activity of estrogen‐quinone metabolizing enzymes, reducing ROS levels and inhibiting oxidative stress (OS)‐induced cancer cell proliferation and angiogenesis." (PMID 30032483, 2018). "Moreover, GSTT1 and GSTM1 polymorphisms are associated with a risk to different cancers and other diseases related to oxidative stress." (PMID 28596482, 2017). "Thus, a validated gene × nutrition interaction such as GSTM1 × cruciferous vegetable consumption leading to reduction of DNA damage is consistent with an association between GSTM1 × cruciferous and reduced cancer risk." (PMID 29270237, 2017). "Null GSTM1 genotypes have been demonstrated to be most commonly associated with risk of cancers." (PMID 27294127, 2016). "Consequently, there is a possibility that smokers carrying the GSTM1 or GSTP1 or GSTM3 risk genotype will be susceptible to cancer if the DNA adducts remain unrepaired." (PMID 24416175, 2014). "Larger studies are needed to testify whether the GSTM1 or GSTT1 polymorphisms could truly impact on different types of cancer." (PMID 24250808, 2013). "Gstm1 encodes the glutathione S-transferase Mu 1, an enzyme involved in phase II detoxification of electrophilic compounds such as products of oxidative stress, environmental toxins and carcinogens and its impairment is associated with increased cancer risk." (PMID 23894592, 2013). "Since smoking has been considered as a risk factor for some types of cancers, we asked whether the GSTM1 or GSTT1 null genotype further facilitates cancer risk in the population of smokers." (PMID 24250808, 2013). "Hence, we performed a meta-analysis with subgroup analysis of eligible studies to acquire more accurate estimation of the association of GSTM1 or GSTT1 with cancer risk." (PMID 24250808, 2013). "In this manner, consuming one portion of broccoli per week if one is GSTM1 positive, or more if one is GSTM1 null, may contribute to a reduction in cancer risk." (PMID 18596959, 2008).
cancer (continued). "Cigarette smoking is an independent risk factor for cervical neoplasia, suggesting that polymorphism at detoxicating enzyme loci such as cytochrome P450 CYP2D6 and glutathione S-transferase GSTM1 may determine susceptibility to these cancers." (PMID 7917923, 1994). "These deletion variants offer significant utility in epidemiological cancer studies, effectively categorizing individuals into two distinct susceptibility classes based on their ability or inability to detoxify potential carcinogens through the metabolic pathways regulated by GSTM1 and GSTT1 genes." (PMID 39619061, 2024). "Thus, ethnic-dependent differences in the prevalence ofGSTT1 and GSTM1 null variants mayinfluence the effect of environmental carcinogens in cancer risk." (PMID 29111561, 2017). "There was significant heterogeneity for GSTM1 allele contrast (null vs. present: P<0.001), Therefore, we used a meta-regression analysis to explore the source of heterogeneity for homozygote comparison (null vs. present) by Ethnicity, cancer types, source of controls and sample size." (PMID 24250808, 2013). "Individuals who have deletions in GSTM1 or GSTT1 may therefore be at increased cancer risk." (PMID 24083102, 2013). "This study aimed at a) confirming the presence of the association between CA and cancer risk in a partially new data set, and b) evaluating the role of GSTM1 and GSTT1 polymorphisms as effect modifiers of this association." (PMID 19270789, 2009). "Null mutations of GSTM1, one of the most important phase II enzymes, are known to abolish enzyme activities and therefore have been linked with increasing incidence of certain cancers, most likely due to increased susceptibilities to environmental toxins and carcinogens." (PMID 19338664, 2009). "In High 2 or Basal groups, downregulation of GSTA1, GSTM1, GSTM2, and GSTT1 gene expression can be correlated with the impaired ability to eliminate carcinogenic compounds and increased cancer risk." (PMID 40426890, 2025). "These authors conclude that GSTM1 null and GSTT1 null genotypes individually significantly contributed to the risk of cancer." (PMID 39595582, 2024). "The aim of this study was to draw a latest conclusion on the relationship between GSTM1, GSTT1 and GSTP1 gene polymorphism and cancer risks among smokers and drinkers." (PMID 38579033, 2024). "KM prevented cancer progression against DEN-induced HCC by an increase in GSTM1, a phase II detoxifying enzyme." (PMID 39916986, 2024). "Subgroup results also showed that drinking increased cancer risks of the stomach with a 1.817-fold, the head and neck with a 3.747-fold and the liver with a 4.244-fold among GSTM1-null carriers." (PMID 38579033, 2024). "Individuals with a slow NAT2 acetyl genome and GSTM1-NULL genotype exhibit impaired metabolic ability, leading to an increased risk of these cancers." (PMID 38957811, 2024). "Broader sample data and appropriate experimental design were needed to further investigate the effects of GSTM1, GSTT1 and GSTP1 polymorphisms on cancer among smokers or drinkers." (PMID 38579033, 2024). "Positive correlation was found between GSTM1 (null/present) and the overall cancer risks among smokers (OR = 1.347, 95% CI: 1.196–1.516, P < .001) and drinkers (OR = 1.748, 95% CI: 1.093–2.797, P = .02)." (PMID 38579033, 2024). "Firstly, we used the Oncomine database to confirm GSTMs mRNA level in multiple cancer types compared to the corresponding para-carcinoma samples, which showed that GSTM1/2/3/4/5 were significantly decreased in many cancers, especially in OC." (PMID 35965498, 2022). "The cancer-related GSTM1, YAP1 and TGM2 genes showed most significant correlation with expression among the FA-HNSCC amplified genes." (PMID 34997070, 2022).
cancer (continued). "In literature, the GSTM1-null and GSTT1-null genotypes have been related to increased risk for several cancers, such as lung and colorectal cancer." (PMID 34006906, 2021). "The ΔCt values of 11 cancer-related genes (HER2, ER, PR, BCL2, CEGP1, Ki67, STK15, STMY3, CD68, GSTM1, and BAG1) were positively associated with HDL." (PMID 34456877, 2021). "SOD2 and GSTM1 are responsible for the detoxification of reactive oxygen species (ROS) and electrophilic compounds, which are produced mainly by mitochondria in cancer cells." (PMID 32717915, 2020). "An interaction between alcohol intake and GSTM1 or GSTT1 was reported previously in cancer of the breast, lung, and stomach." (PMID 31999731, 2020). "The subgroups include proliferation genes (Ki67, STK15; Survivin, CCNB1, MYBL2), invasion genes (MMPP11, CTSL2), HER2 genes (GRB2, HER2), estrogen genes (ER, PGR, BCL2, SCUBE2), and other cancer related genes (GSTM1, CD68, BAG1)." (PMID 33665165, 2020). "The proportion of CML cancer attributable to the interaction of smoking and GSTM1 null, GSTT1null, and GSTP1 M* was 42%, 39%, and 13%, respectively." (PMID 31111691, 2019). "Previous studies already showed that the null GSTM1 and GSTT1 genotypes were likely to have an association with higher risk of a different type of cancers." (PMID 30976200, 2019). "Individuals who completely lack GSTM1 and GSTT1 enzyme activity due to the inherited homozygous loss of these genes are more likely to have a higher risk of acquiring cancer." (PMID 30803216, 2019). "The proportion of CML cancer attributable to the interaction of smoking and GSTM1 null was 42% and was 39%, 13% for GSTT1 null and GSTP1 M*, respectively." (PMID 31111691, 2019). "In particular, GSTT1-1 and GSTM1-1 null genotypes, as well as GSTP1-1 variants, were studies and showed a positive correlation with cancer risk 24,32,35–42." (PMID 29362397, 2018). "The deletion of GSTM1 and GSTT1 genes (both null genotype) has been associated with a rise in a number of cancers, possibly due to an amplified susceptibility to the harmful effects of oxidative stress, environmental toxins and carcinogens." (PMID 29795558, 2018). "Previous studies have explored the relationship between GSTM1/GSTT1 deletion polymorphisms and cancer susceptibility." (PMID 27911277, 2017). "Among the xenobiotic metabolizing enzymes, CYP1A1, GSTM1 and GSTT1 have been projected as the potential modulators of cancer susceptibility." (PMID 27090234, 2016). "GSTM1 is one of the most key subclasses of GSTs, which has potent protective role against cancer compared to other GST subtypes." (PMID 27294127, 2016). "In particular, the expression level of GSTM1 has a protective effect, and was associated with reduced mortality in participants of ilSIRENTE study, whereas GSTT1 was associated with lower cancer risk, longevity and aging in human granulosa cells." (PMID 27545843, 2016). "The result of analysis of the GST family and cancer shows significant ORs of GSTM1 and GSTM2 on cancer [1.110 (95% CI: 1.080–1.141) and 1.125 (95% CI: 1.073–1.180), respectively]." (PMID 27045371, 2016). "GSTM1 has been identified to be involved in the pathogenesis and development of certain cancers, inclusive of colorectal cancer." (PMID 26219826, 2015). "The conjugation of glutathione prevent damage resulting from exposure to toxic chemicals and to normal oxidative products of cellular metabolism, the association between GSTM1 and GSTT1 copy number and increased risk of cancer is, at first glance, unexpected." (PMID 25198353, 2014). "Among the GSTs, the association of the GSTM1, GSTT1 and GSTP1 genotypes with their individual susceptibilities to cancer has been extensively studied." (PMID 23717494, 2013).
cancer (continued). "GST-μ, GST-τ, and GST-π are encoded by the GSTM1, GSTT1, and GSTP1 genes, respectively; and these 3 genes have been studied in association with genetic susceptibility to cancer." (PMID 24083102, 2013). "Based on these backgrounds, the association between GSTM1 and GSTT1 has been intensively investigated polymorphisms and risk of a variety of cancer, but the results remain contradictory." (PMID 24250808, 2013). "The risk of cancers is frequently higher in individuals with combined mutant genotypes of CYP1A1*2A and GSTM1 null genotype than in those with CYP1A1 or GSTM1 gene alone." (PMID 24151610, 2013). "In conclusion, this meta-analysis demonstrates that GSTM1 and GSTT1 null genotypes are risk factors in multiple types of cancers." (PMID 24250808, 2013). "Given the biological function of GSTs, many epidemiological studies have focused on the association of GSTM1 and GSTT1 polymorphisms with cancer risk in human." (PMID 24250808, 2013). "We reviewed here published papers where an estimate of gene–smoking interaction between GSTM1 or GSTT1 polymorphisms and cancer risk was available." (PMID 24250808, 2013). "Over the past decades, an increasing number of studies have investigated the association between GSTM1 or GSTT1 polymorphisms and cancer risk in human." (PMID 24250808, 2013). "Herein, we aimed to assess the possible associations of the GSTM1 and GSTT1 null genotype in cancer risks." (PMID 24250808, 2013). "Four genes showed significant methylation-expression association in all five individual cancer types, BST2, SLA2, GSTT1, and GSTM1." (PMID 23742247, 2013). "When the analysis was performed based on their smoking history, the risk associated of GSTM1 null and GSTT1 null genotypes with cancer is further increased (for GSTM1: OR = 2.66; 95%CI = 2.19–3.24; for GSTT1: OR = 2.46; 95%CI = 1.83–3.32, respectively)." (PMID 24250808, 2013). "The polymorphisms in GSTM1 and GSTT1 have been investigated in cancer for a long time; however, only recently have some studies investigated the association of various cancers with GSTP1 variants." (PMID 23077566, 2012). "Interindividual variation in the GSTM1 genotypes has been investigated in relation to various types of cancers." (PMID 22900055, 2012). "The possible role of GSTM1 and GSTT1 genetic polymorphisms as effect modifiers of the association between CA frequency and cancer risk was tested in the Bayesian models (model M3 vs. model M2)." (PMID 19270789, 2009). "Previous evidence implicates polymorphisms of GSTM1 and GSTT1, candidates of phase II enzymes, as risk factors for various cancers." (PMID 19338664, 2009). "A similar multivariate model was used to estimate if the GSTM1 null and GSTT1 null genotypes were a risk factor for all cancers (model M2 vs. model M1)." (PMID 19270789, 2009). "The prevalence of GSTM1 (0/0) genotype in the cancer group was 49% compared to 52.6% in control group." (PMID 17897446, 2007). "The genetic polymorphisms at the GSTM1 and GSTT1 genes were reported to be deletion of nucleotides (referred to as null GSTM1 and null GSTT1 alleles), which have been associated with susceptibility to cancer." (PMID 17335581, 2007). "Glutathione S-transferase (GSTM1 and / or T1) null genotype modulates the risk of developing UADT cancer (primary as well as second cancer)." (PMID 15790417, 2005). "Patients with second (synchronous and metachronous) cancers in the UADT also have a higher frequency of GST null genotype (particularly GSTM1 and T1) as compared to those with single cancers." (PMID 15790417, 2005). "Indeed, several chemoprevention trials have reported that the reduction in biomarkers of cancer risk (e.g., aflatoxin-DNA adducts) following SFN intervention was predominantly observed in subjects with the GSTM1-null genotype." (PMID 41246347, 2025).
cancer (continued). "And it was shown in this study that GSTM1, GSTT1, and GSTP1 polymorphisms, alone or in combination with smoking or drinking, might affect the overall cancer risks differently, and the effects might be related to ethnicities." (PMID 38579033, 2024). "The significance of GSTM1 and GSTT1 polymorphisms extends to their potential implications within molecular pathways, pivotal in understanding individual susceptibility to diseases such as cancer." (PMID 39619061, 2024). "For alcohol consumption, 12 articles (4238 cases and 5394 controls) were about the association between GSTM1 and cancers, 8 articles (2949 cases and 4025 controls) were about GSTT1 and cancers and 5 articles (1898 cases and 2527 controls) were about GSTP1 and cancer among drinkers." (PMID 38579033, 2024). "GSTM1 (null/present) might rise the overall cancer risks in both smokers (I2 = 68.20%, OR = 1.347, 95% CI: 1.196–1.516, P < .001) and nonsmokers (I2 = 54.70%, OR = 1.423, 95% CI: 1.270–1.594, P < .001)." (PMID 38579033, 2024). "Otherwise, the representativeness might be stronger to further explore the interaction between GSTM1, GSTT1 and GSTP1 polymorphisms and cancers among drinkers." (PMID 38579033, 2024). "And alcohol consumption might be a synergistic factor in promoting cancer risks of the liver, the head and neck and the stomach among GSTM1-null carriers." (PMID 38579033, 2024). "Deletion of the GSTM1 gene can lead to inactivation of GST-μ, altering a resistance to poisons and carcinogens, what can result in the loss of detoxification capacity and increasing the risk of cancer development." (PMID 37819495, 2023). "In meta-analysis, it was concluded that the GSTM1-null genotype was significantly associated with the risk of cancer development for the Asian population, but no significance effect of this SNP in the Caucasian population was noted." (PMID 37819495, 2023). "The meta-analysis conducted in 2012 was found that GSTM1 null genotype, GSTM1 and GSTT1 double null genotype or GSTT1 null genotype and rs1695 polymorphism within the GSTP1 gene can correlate with an increased risk of cancer development." (PMID 37819495, 2023). "It has been suggested that individuals lacking GSTT1 and or GSTM1 have an impaired ability to detoxify environmental xenobiotics and are thus at elevated risk for cellular damage and resultant cancer." (PMID 36316809, 2023). "In this context, KCNAB2, H2AFY, DOCK2 and GSTM1 in our signature significant high expression in high‐risk group compare to low‐risk group and related to poor prognosis, and all genes except KCNAB2 in signature have been reported to be involved in cancer." (PMID 33259129, 2021). "GSTM1 and GSTT1 homozygous deletions are associated with reduced function of xenobiotics detoxification, increased susceptibility to cytogenetic damage, and increased risk of cancer." (PMID 32882964, 2020). "Additionally, GSTM1, exclusively detected in RBVS exosomes, has been implicated in cancer chemoresistance." (PMID 32545553, 2020). "To date, GSTM1-null and GSTT1-null genotypes have been the focus of numerous investigations attempting to elucidate the effect of their deficiency and susceptibility to cancers." (PMID 32183092, 2020). "Null mutations of GSTM1 and GSTT1 phase II enzymes have been shown to halt enzyme activity resulting in greater susceptibility to environmental toxins and carcinogens related to an increased risk of cancer." (PMID 32882964, 2020). "Therefore, people with inherited two null variants of the glutathione S-transferase Mu 1 (GSTM1) and glutathione S-transferase theta 1 (GSTT1) alleles are more resistant to cancer development due to longer exposure to ITCs." (PMID 31003534, 2019). "However, this increased ASK1 activity leads to HPAC cancer cell death only by reduced Trx and GSTM1 expression." (PMID 30523245, 2018). "GSTM1 isoenzyme also detoxifies certain anti-cancer drugs, mostly including alkylating agents." (PMID 30487385, 2018).